FGF23 (fibroblast growth factor 23)
Diseases named in the same sentence as FGF23 in open-access papers (continued):
Sharing a sentence is not in itself a finding about the gene and the disease.
renal fibrosis (continued). "Although further work needs to be done to substantiate this hypothesis, it is tempting to speculate that excessive FGF23 may be the missing link between dietary phosphate and renal fibrosis in our model." (PMID 34290280, 2021). "This study sought to investigate whether FGF23 plays an important role in CRS-induced renal fibrosis." (PMID 33460402, 2021). "Tubule-derived FGF23 may amplify myofibroblast activation in acute renal injury, and might provide a novel therapeutic target in renal fibrosis." (PMID 28611350, 2017). "To investigate the putative role of FGF23 as a mediator of renal fibrosis, we sought evidence of ectopic renal production of FGF23 in response to unilateral ureteric obstruction (UUO), and determined the effects of FGF23 on renal interstitial fibroblast activation and function in vitro." (PMID 28611350, 2017). "Thus, we speculate that FGF-23 may promote renal fibrosis via TGFβ/Smad and Wnt/β-catenin signalling." (PMID 37016338, 2023). "Animal studies of ureteral obstruction (UUO) have shown that tubule-derived FGF-23 can enhance the activity of myofibroblasts during AKI, possibly promoting the signalling cascade of renal fibrosis by activating TGF-β channels." (PMID 37016338, 2023). "FGF23 promotes the profibrotic signaling pathways in renal fibroblasts in AKI, leading to renal fibrosis and CKD." (PMID 37626956, 2023). "Moreover, FGF-23 upregulation may result in renal fibrosis via TGF-β and Wnt/β-catenin activation." (PMID 37016338, 2023). "In addition, FGF23 stimulates renal fibrosis, exerts pro-inflammatory effects, and disrupts normal immune function." (PMID 32512806, 2020). "Renal FGF23 expression in uremic rats does not contribute to increased circulatory FGF23 levels but local production may further trigger renal fibrosis in these animals." (PMID 30405444, 2018). "Our findings indicate that FGF23 promotes renal fibrosis may not depend on Klotho." (PMID 33460402, 2021). "Therefore, we hypothesized that FGF23 may also play a role in renal fibrosis, either with Klotho or independent of Klotho." (PMID 33460402, 2021).
familial tumoral calcinosis (18 papers, 2009 to 2026). Tumoral calcinosis is a phosphocalcic metabolism anomaly, particularly among younger age groups and characterized by the presence of calcified masses in the juxta-articular regions (hip, elbow, ankle and scapula) without joint involvement. "Hyperphosphatemic familial tumoral calcinosis (HTC) is a rare disease caused by autosomal recessive loss of function variants in the genes encoding fibroblast growth factor 23 (FGF-23), Klotho, or GalNAc-T3." (PMID 41675205, 2026). "Hyperphosphatemic familial tumoral calcinosis (FTC) is a rare genetic disorder resulting from the mutations in FGF23, GALNT3, or KL genes." (PMID 34199304, 2021). "The metabolic mirror of ADHR is familial tumoral calcinosis, which is associated with pathologic increase of bone mineral density and is caused by loss of function mutations in the FGF23 or GalNT3 gene." (PMID 30971944, 2019). "Mutations in FGF23, KL, and GALNT3 have been identified as the cause for the development of hyperphosphatemic familial tumoral calcinosis (HFTC)." (PMID 34270404, 2021). "Hyperphosphatemic familial tumoral calcinosis (HFTC) is a rare autosomal recessive disorder caused by mutations in FGF23, GALNT3, KLOTHO, or FGF23 autoantibodies." (PMID 33977199, 2021). "Hyperphosphatemic familial tumoral calcinosis (HFTC) is a rare and disabling disorder of fibroblast growth factor 23 (FGF23) deficiency or resistance." (PMID 32457699, 2020). "Hyperphosphatemic familial tumoral calcinosis (HFTC) is a very rare disorder of phosphate homeostasis resulting from decreased fibroblast growth factor 23 (FGF23) synthesis or activity." (PMID 30015621, 2019). "Inactivating autosomal recessive mutations in fibroblast growth factor 23 (FGF23), klotho (KL) and polypeptide N-acetylgalactosaminotransferase 3 (GALNT3) genes lead to a rare disorder, hyperphosphatemic familial tumoral calcinosis (HFTC)." (PMID 30015621, 2019). "Hyperphosphatemic familial tumoral calcinosis (HFTC) is a rare monogenic disorder with disturbances in the hormonal regulation of phosphate levels by FGF23, leading to soft tissue calcifications." (PMID 25249269, 2014). "Hyperphosphatemic Familial Tumoral Calcinosis (HFTC) and Hyperphosphatemic Hyperostosis Syndrome (HHS) are associated with autosomal recessive mutations in three different genes, FGF23, GALNT3 and KL, leading to reduced levels of fibroblast growth factor 23 (FGF23) and subsequent clinical effects." (PMID 25249269, 2014). "Hyperphosphatemic familial tumoral calcinosis (HFTC) is a rare and disabling disorder resulting from disturbances in FGF23-mediated phosphate regulation." (PMID 32457699, 2020).
Fanconi syndrome (18 papers, 2015 to 2026). "The FGF23 concentration can distinguish between proximal renal tubule dysfunction such as Fanconi syndrome (low FGF23 concentration) or FGF23-dependent causes such as TIO (normal or elevated FGF23 concentrations)." (PMID 35665817, 2023). "The clinical course provided evidence supporting the hypothesis of Fanconi syndrome predominating on renal phosphate leak as a consequence of FGF23 excessive secretion in the setting of acute hepatitis, with complete resolution of laboratory abnormalities coinciding with hepatic recovery." (PMID 39525686, 2024). "Interestingly, FGF23 may also be increased in tenofovir-induced Fanconi syndrome, via yet unknown mechanisms." (PMID 33815294, 2021). "However, there was a tendency towards low parathyroid hormone (PTH) and low fibroblast growth factor 23 (FGF23) levels, likely reflecting the consequences of chronic tubular phosphate wasting, although Fanconi syndrome appeared to be well controlled in these patients." (PMID 35011732, 2022).
Cognitive impairment (17 papers, 2016 to 2025). Abnormal cognition is characterized by deficits in thinking, reasoning, or remembering. "We therefore evaluated the independent association of intact FGF-23 with baseline cognitive function and incident cognitive impairment." (PMID 33306729, 2020). "FGF-23 deficiency causes hippocampal-dependent cognitive impairment as measured by impaired fear and object location memory." (PMID 30911673, 2019). "We report that, similar to Klotho-deficient mice, FGF-23-deficient mice develop dose-dependent, hippocampal-dependent cognitive impairment." (PMID 30911673, 2019). "We speculate that dialysis age, increased BMI, decreased blood calcium, and the abnormal level of FGF-23 may be independent risk factors for cognitive impairment in hemodialysis patients." (PMID 40950978, 2025). "FGF23-deficient mice exhibit dose-dependent cognitive impairment related to the hippocampus." (PMID 41007258, 2025). "The ROC curve analysis further revealed that FGF-23 has diagnostic value for cognitive impairment." (PMID 40950978, 2025). "Age, dialysis age, increased BMI, decreased blood calcium, and the abnormal level of FGF-23 may be independent risk factors for cognitive impairment in hemodialysis patients." (PMID 40950978, 2025). "FGF-23 knockout mice also exhibited cognitive impairment in several in vivo studies, which may be associated with dysregulation of phosphate homeostasis and cytotoxicity." (PMID 37214403, 2023). "While previous studies evaluating the effect of FGF23 on cognition have been equivocal in adults, data from the CKiD cohort suggests that a higher plasma FGF23 level is associated with higher cognitive impairment and lower performance in tests of executive function." (PMID 35280279, 2022). "Finally, a cross-sectional observational study in 69 hemodialysis patients recently demonstrated an association of cognitive impairment with intracranial artery calcification and low FGF23." (PMID 34536161, 2021). "Association of FGF-23 with incident cognitive impairment in the health ABC study." (PMID 33306729, 2020). "There are limited published data on the association of FGF-23 with cognitive impairment." (PMID 33306729, 2020). "There are several potential mechanisms which may explain observed associations between FGF-23 and cognitive impairment." (PMID 33306729, 2020). "Kidney disease is strongly associated with cognitive impairment and therefore the observed association of FGF-23 and cognitive impairment may represent residual confounding with kidney function, kidney disease severity." (PMID 33306729, 2020). "Given the potential for FGF-23 to impact the brain, we hypothesized that high FGF-23 concentrations would be associated with the development of cognitive impairment." (PMID 33306729, 2020). "If an indirect effect of FGF-23 deficiency drives mouse hippocampal-dependent cognitive impairment, correction of phosphate homeostasis may either correct or prevent development of cognitive effects and do so across species impaired by altered FGF-23 levels." (PMID 30911673, 2019). "Thus similar to what is observed with Klotho deficiency, FGF-23-deficient mice rapidly develop hippocampal-dependent cognitive impairment evidenced by impaired fear and spatial memory task performance." (PMID 30911673, 2019). "If this effect results from failure of FGF-23 signal transduction through Klotho, FGF-23-deficient mice may be expected show hippocampal-dependent cognitive impairment." (PMID 30911673, 2019). "It is unclear whether overexpression of FGF-23 induces cognitive impairment because of its role in learning and memory, or as an indirect consequence of the peripheral illness caused by high levels of FGF-23." (PMID 30911673, 2019). "Similarly, when FGF23 was modeled as a continuous variable, in the unadjusted model, higher FGF23 concentrations were associated with higher odds of developing cognitive impairment (OR per doubling of FGF23 1.12, 95%CI 1.03,1.33)." (PMID 27812184, 2016).
Cognitive impairment (continued). "Fibroblast growth factor 23 (FGF23) is a hormone that inhibits vitamin D activation yet few studies examined whether FGF23 is associated with cognitive impairment." (PMID 27812184, 2016). "Next, we used survival analysis to predict the effects of different levels of FGF-23, BMI and calcium on the occurrence of cognitive impairment after 4 years." (PMID 40950978, 2025). "In the unadjusted model, when compared to the lowest quartile of FGF23 (FGF23 <53 RU/ml), the highest quartile of FGF23 (FGF23 >100 RU/ml) had a 73% higher odds of incident cognitive impairment (OR 1.73, 95% confidence interval [CI] 1.21,2.47)." (PMID 27812184, 2016). "Odds ratio (95% confidence interval) of incident cognitive impairment according to baseline fibroblast growth factor 23 concentrations." (PMID 27812184, 2016). "Therefore, a longer follow-up study on the prognosis of MHD patients participating in this experiment is needed to further explore the effects of age, dialysis age, BMI, blood calcium, and the level of FGF-23 on cognitive impairment in MHD patients." (PMID 40950978, 2025). "Interestingly, this FGF23-induced cognitive impairment was alleviated when mice were fed a high-phosphorus diet, underscoring the role of FGF23-mediated phosphorus metabolism in cognitive health [1050]." (PMID 40407975, 2025). "Moreover, uremic toxins such as phosphate, para-cresyl sulfate (PCS), indoxyl sulfate (IS), and fibroblast growth factor 23 (FGF23) have been reported to increase the risks of cognitive impairment in patients with CKD." (PMID 39671124, 2024). "In other words, FGF-23 may indirectly trigger cognitive impairment by aggravating cerebrovascular damage." (PMID 37214403, 2023). "Mice deficient for FGF23 show cognitive impairment, too, but without defects in gross structure or development of the brain and no changes in hippocampal synaptic plasticity." (PMID 34536161, 2021). "This indicates that there is an interaction between Klotho and fibroblast growth factor-23, which jointly regulates the anti-oxidative stress of the body, improves the cognitive impairment of rats, and plays a role in protecting the kidney function, thus delaying aging." (PMID 32042011, 2020). "We utilized an assay which measures only the biologically active intact FGF-23; use of the c-terminal assay may yield FGF-23 levels including fragments that are increased in states of inflammation, a potential confounder for cognitive impairment." (PMID 33306729, 2020). "They showed that FGF-23 was significantly up-regulated in patients with cognitive impairment." (PMID 30115946, 2018). "Furthermore, a cross-sectional study with 263 prevalent patients with HD showed high FGF23 that may have contributed to cognitive impairment." (PMID 35145471, 2021). "As increases in FGF-23 appear primarily driven by decreased kidney function, there remains uncertainty about FGF-23’s potential role in the development of cognitive impairment in groups at higher risk for both cognitive impairment and kidney disease, such as older adults." (PMID 33306729, 2020). "Our findings suggest a potential relationship between cognitive impairment in MHD patients and FGF-23 levels." (PMID 40950978, 2025). "Thus, it is possible that hippocampal-dependent cognitive impairment could be the result of an increasingly toxic brain micro-environment caused by FGF-23 deficiency and a resulting lack of normal ion homeostasis." (PMID 30911673, 2019). "In addition, CPMD is accompanied by increased levels of FGF23 and PTH and decreased levels of α-Klotho and calcitriol, consequently leading to cerebrovascular diseases and related cognitive impairment." (PMID 39407758, 2024). "Across quartiles of FGF-23, those in the highest quartile compared to the lowest quartile were the most likely to develop cognitive impairment, though this result was not statistically significant." (PMID 33306729, 2020).
Cognitive impairment (continued). "In summary, we found no between FGF-23 and either cross-sectional cognitive function or longitudinal cognitive impairment." (PMID 33306729, 2020). "Although the question whether FGF23 plays a direct role in cognitive impairment is not solved yet, cognitive dysfunctions occur in almost all stages of CKD and need to be carefully addressed in further studies." (PMID 34536161, 2021).
coronary artery calcification (17 papers, 2012 to 2026). Calcification of the coronary artery, used as a measure of coronary atherosclerosis, a risk factor for myocardial infarction. "In logistic regression analysis, the higher coronary artery calcification progression was significantly associated with serum FGF23, phosphorus levels, and baseline coronary artery calcification score." (PMID 30970562, 2019). "In this prospective study, we aimed to investigate the association of serum FGF-23 with progression of coronary artery calcification in HD patients." (PMID 24180481, 2013). "Intact- FGF23 was also found to correlate with progression of coronary artery calcification over the course of a year among 74 hemodialysis patients." (PMID 28870151, 2017). "In this prospective study, we aimed to investigate the possible effects of serum FGF-23 on the progression of coronary artery calcification in HD patients." (PMID 24180481, 2013). "Fibroblast growth factor 23 (FGF23) is a circulating regulator of phosphate and vitamin D metabolism and is associated with coronary artery calcification, and has been implicated in the pathogenesis of cardiovascular disease." (PMID 24015259, 2013). "Log coronary artery calcification (log CAC score) (r = 0.28, P = 0.006), and log fibroblast growth factor-23 (log FGF-23) (r = 0.23, P = 0.03) were also correlated with ssEFV." (PMID 23351146, 2013). "The aim of this study was to investigate the relationships between FGF23, OPG, and coronary artery calcifications (CAC) in this population and to attempt identification of the most powerful biomarker of CAC: FGF23?" (PMID 22567137, 2012).
malnutrition (17 papers, 2008 to 2024). Inadequate nutrition resulting from poor diet, malabsorption, or abnormal nutrient distribution. "The results of previous studies performed at our center have indicated that abnormal FGF23, klotho, and fetuin-A levels and malnutrition represent risk factors for abdominal aortic calcification in patients with ESRD." (PMID 34759797, 2021). "A second aim is to assess the influence of NHD on the biomarkers fibroblast growth factor-23 and sclerostin which are thought to be associated with malnutrition and mortality in patients on haemodialysis." (PMID 28460640, 2017). "Taken together, calcium-induced FGF23 elevation may increase the risk of infection-related death by affecting host defense mechanisms and inducing inflammation and malnutrition." (PMID 32286455, 2020). "FGF-23 may be associated with low body mass index (BMI) and malnutrition." (PMID 28460640, 2017). "A study on rats reported that maternal malnutrition in the prenatal period resulted in low FGF23 levels." (PMID 39045952, 2024). "Some authors have also correlated malnutrition to low levels of newly discovered hormones like fibroblast growth factor 23 (FGF 23)." (PMID 36331725, 2023). "In patients with severe malnutrition and a very limited phosphate intake, phosphate restriction is considered to be responsible for decreased FGF23 levels." (PMID 18412981, 2008). "Low FGF-23 levels may suggest limited FGF-23 production due to malnutrition, a condition in which an energy-saving mechanism might operate in bone marrow and osteocytes." (PMID 39684548, 2024). "In recent years, the influence of nontraditional risk factors, such as FGF23, klotho abnormality, microinflammatory state, and malnutrition on vascular calcification has attracted much attention from scholars." (PMID 34367315, 2021). "Considering that the derangement of FA metabolism characterizes CKD due to chronic inflammation, oxidative stress, and malnutrition accelerating CKD and CVD progression, in the present study, we investigate if a correlation among FGF23, MCP1, and PUFA occurs." (PMID 36498673, 2022).